MGMT (O-6-methylguanine-DNA methyltransferase)
Diseases named in the same sentence as MGMT in open-access papers (continued):
Sharing a sentence is not in itself a finding about the gene and the disease.
glioma (continued). "The heatmap showed the relationship between high‐ and low‐risk groups and clinical features of glioma patients, such as gender, age, WHO grade, IDH mutation status, KPS, 1p/19q codeletion, TERT promoter status, and MGMT promoter methylation status, in TCGA database." (PMID 36560848, 2023). "Furthermore, the nitric oxide donor S-nitroso-N-acetylpenicillamine was reported to downregulate MGMT expression in glioma, while the anti-estrogen tamoxifen was shown to promote MGMT degradation in colorectal cancer cells." (PMID 36902118, 2023). "We measured the expression of the DNA repair enzyme MGMT to assess whether the glioma cells had TMZ resistance." (PMID 37534227, 2023). "The aim of this study is to investigate whether cognitive functioning has a prognostic value for survival in patients with IDH1-wt, MGMT-unmet high-grade gliomas." (PMID 38168519, 2023). "Moreover, most APS gliomas are low-grade gliomas with a high ratio of IDH and TERT mutations and MGMT methylation." (PMID 38111070, 2023). "Glioma patients with MGMT CpG promoter methylation have shown prolonged PFS and OS." (PMID 37182181, 2023). "Future studies could focus on the recently recognized role of MGMT promoter methylation intratumoral heterogeneity in glioma biology and response to therapy." (PMID 37919784, 2023). "MGMT expression is regulated in gliomas by methylation of the promoter region." (PMID 37283490, 2023). "MGMT methylation is one of the independent predictors of good prognosis of glioma patients." (PMID 36856519, 2023). "Importantly, the expression of tyrosine metabolizing enzymes was able to discriminate the extent to which clinical features including grade, IDH status, 1p19q status, and MGMT, suggesting their potential as tumor markers in glioma." (PMID 37786553, 2023). "Additionally, a new association between HH signaling and DNA repair mechanisms with the participation of O-6-methylguanine-DNA methyltransferase (MGMT) was identified in gliomas." (PMID 37626893, 2023). "The study enrolled 49 patients with IDH wild-type, MGMT-unmethylated high-grade gliomas." (PMID 38168519, 2023). "Based on four signature genes (AHR, DACH1, MGMT, and YAP1), a risk model for predicting glioma sensitivity to temozolomide was constructed, and the results of timeROC in both the training and validation sets showed that the model had good predictive performance." (PMID 36959804, 2023). "Frontal lobe (35.3%) was the preferred location for tumors with both methylated and unmethylated MGMT promoter.This may be due to the fact that frontal lobe being the largest is also the commonest site for gliomas." (PMID 39760063, 2023). "Additionally, MGMT promoter methylation has important significance in predicting the response to temozolomide (TMZ) in glioma patients, which indirectly reflects the prognosis of patients." (PMID 36861130, 2023). "In the majority of IDH-mutated gliomas, the MGMT promoter is also methylated, but vice versa is not true." (PMID 38168519, 2023). "GBMs prioritize the assessment and inclusion of MGMT promoter methylation as an essential component of molecular diagnostics and treatment for all high-grade gliomas (grades 3 and 4) where studies have reported that up to 60% of GBMs cases exhibit MGMT promoter methylation." (PMID 37242509, 2023). "MGMT methylation status represents another molecular feature of gliomas." (PMID 38027011, 2023). "Similarly, the methylation status of MGMT is widely used in glioma patients as a predictive biomarker of response to alkylating chemotherapy agents and is included on National Comprehensive Cancer Network guidelines." (PMID 36831050, 2023). "In addition, heterogeneity in gliomas also depends on molecular characteristics, such as MGMT status, IDH, and ARTX." (PMID 37258577, 2023).
glioma (continued). "We also sought to determine whether ceramidase expression correlated with MGMT promoter methylation status, because MGMT promoter-unmethylated gliomas are more resistant to TMZ." (PMID 38086808, 2023). "MGMT is an essential biomarker in glioma drug resistance prediction." (PMID 37779868, 2023). "Therefore, this study constructed and validated a radiomics model for predicting the subtype of IDH mut combined with MGMT meth in glioma via noninvasive radiomics based on preoperative MRI." (PMID 36900232, 2023). "The IDH mutation and 1p/19q codeletion take place more in the low-grade gliomas, but the MGMT promoter mutation did not display this rule." (PMID 35669186, 2022). "We hypothesized that coexisting factors or interactions between variables might induce the increment of ADC in TERT-wt and MGMT-m gliomas." (PMID 36471242, 2022). "Moreover, IDH mutations have been established as the most powerful positive prognostic factor for survival in gliomas, followed by age, tumor grade, and MGMT promoter methylation status." (PMID 35267433, 2022). "Furthermore, METTL3 promotes the temozolomide (TMZ) resistance of glioma cells by increasing DNA repair genes O6-methylguanine-DNA methyltransferase (MGMT) and alkylpurine–DNA–N-glycosylase (ANPG)." (PMID 36008936, 2022). "By integrating SC2I, age, gender, MGMT promoter status, IDH mutation status, WHO grade, and original subtype, we established a nomogram to accurately predict the 1-, 2- and 3-year survival probability of glioma patients." (PMID 36552760, 2022). "EANO recommends evaluating the MGMT promoter methylation status of elderly or frail patients with high-grade gliomas to determine whether temozolomide is required." (PMID 36009577, 2022). "In contrast, glioma patients with lower MGMT promoter DNA methylation had higher exosomal MGMT." (PMID 35682901, 2022). "Similarly, an evaluation of cerebral microbleeds in gliomas has proved to be of significant value in predicting the glioma grade, IDH1 mutation, and MGMT methylation; this is affected by evaluating intratumoral susceptibility signal (ITSS) grades." (PMID 36289752, 2022). "With advances in targeted tumor treatment research and technology, there have been several breakthroughs in the identification of glioma molecular markers, such as isocitrate dehydrogenase (IDH) mutations and O6-methylguanine-DNA methyltransferase (MGMT O6) promoter methylation." (PMID 36199426, 2022). "Thus, combined with the knowledge gained from an earlier study, it is evident that MGMT transportation in exosomes plays an important role in glioma TMZ resistance." (PMID 35682901, 2022). "At present, glioma patients’ treatment options mainly depend on WHO classification (WHO I-IV), as well as molecular subtypes, like IDH mutations, 1p19q deletion status, and MGMT methylation." (PMID 35903107, 2022). "Glioma patients with low expressions of MGMT protein were more likely to have favorable outcomes." (PMID 35968285, 2022). "However, gliomas were grouped according to the status of IDH mutation and MGMT promoter methylation in this study, and the results of WHO grade of tumors did not affect the main results of this study." (PMID 36711137, 2022). "Subsequently, we found that this signature could distinguish the clinical and molecular features of gliomas, including WHO grade, TCGA subtype, IDH mutational status, 1p19q co-deletion and MGMT promoter methylation." (PMID 35236310, 2022). "MGMT is involved in the development of resistance to alkylating chemotherapeutic drugs in glioma, and its promoter methylation has been considered as a potential biomarker for the outcome of patients with glioma." (PMID 35109832, 2022).
glioma (continued). "However, it is not in regular use for the lower-grade glioma as a prognosticator, and most of the low histological grade IDH mutant gliomas are likely to be MGMT methylated." (PMID 35558510, 2022). "Moreover, SHOX2 was highly expressed in glioma tissues with O-6-methylguanine-DNA methyltransferase (MGMT)-unmethylation and temozolomide (TMZ) resistant glioma cell lines, and associated with MGMT expression." (PMID 36118887, 2022). "Additionally, BIRC5 expression is also associated with histology subtypes, IDH1 mutation, 1p/19q chromosomal co-deletion, chemotherapy status, and MGMT promoter methylation status, well-established molecular characteristics of gliomas." (PMID 35309512, 2022). "Over the last decade, isocitrate dehydrogenase (IDH) mutations, chromosome 1p/19q deletions, MGMT and TERT promoter methylations, and histone mutations have all served as glioma biomarkers; these markers play key roles in glioma classification and treatment decisions." (PMID 36579333, 2022). "For example, in this study, HGGs were more likely to have MGMT-um and IDH-wt than LGGs (P = 0.002 and P < 0.0001, respectively), and consequently, the ADC values in MGMT-unmethylated gliomas might be affected by the tumor grading and concurrent IDH-wt." (PMID 36471242, 2022). "Gliomas with unmethylated and methylated MGMT promoters had similar ascorbate levels (p = 0.96)." (PMID 36050369, 2022). "Therefore, MGMT promoter methylation status is an independent predictor of prognosis in patients with gliomas." (PMID 35807084, 2022). "Although MGMT promoter methylation has limited diagnostic value, it is of great importance to guide treatment decisions on the use of chemotherapy with alkylating agents for patients with IDH1-wild-type gliomas and GBMs." (PMID 35372034, 2022). "Besides, unmethylated MGMT promoter correlated with higher APM signature score in pan-glioma and LGG samples, respectively." (PMID 35418980, 2022). "A recent study revealed that MGMT-negative deficient gliomas were responsive to TMZ and would still develop therapeutic resistance, leading to treatment failure." (PMID 35145081, 2022). "Due to hypermethylation in recurrent gliomas treated with TMZ, deficiency of MMR pathway and MGMT expression led to enhancement of DNA repair systems such as HR, NHEJ and base excision repair, suggesting that a hyperactive DNA repair system was essential for TMZ-resistance." (PMID 35145081, 2022). "Researcher should also determine whether paeoniflorin affect the sensitivity of glioma cells to TMZ by altering the expression of MGMT." (PMID 36046834, 2022). "A total of 111 patients with complete MRI imaging data and complete results of MGMT promoter methylation status were enrolled in the training (89 patients) and validation cohorts (22 patients), including 56 patients with MGMT methylated gliomas and 55 patients with MGMT unmethylated gliomas." (PMID 35743511, 2022). "Therefore, the detection of methylation status of MGMT promoter has become an important clinical procedure for the prognosis of glioma patients." (PMID 35931979, 2022). "Nowadays, new molecular subtypes have been widely clinically utilized to predict the prognosis and therapy outcomes of the glioma patients, such as IDH (isocitrate dehydrogenase) mutation and 1p/19q codeletion on chromosomal and 6-O-methylguanine-DNA methyltransferase (MGMT) promoter methylation." (PMID 36111134, 2022). "Clinical glioma samples (11 low-grade, 26 high-grade) were analysed for ascorbate, global DNA methylation and hydroxymethylation, and methylation status of the O-6-methylguanine-DNA methyltransferase (MGMT) promoter." (PMID 36050369, 2022). "This information is relevant to MGMT’s role in glioma cell TMZ resistance." (PMID 35682901, 2022). "However, few studies evaluate the feasibility of ADC in predicting TERT and MGMT status in WHO grade II-IV gliomas." (PMID 36471242, 2022). "In this study, we therefore assessed MGMT methylation in IDH-mutant gliomas." (PMID 35701666, 2022).
glioma (continued). "Molecular data such as IDH mutation and MGMT promotor status as known prognostic and predictive parameters in supratentorial gliomas were not available in all cases." (PMID 34342680, 2022). "Friebel and coworkers showed in a single-cell transcriptomic study that CD16-positive NK cells primarily accumulate in IDH1 mutated gliomas and further in those with negative MGMT promoter methylation status." (PMID 36361720, 2022). "With low MGMT level, TMZ-R gliomas exhibited a gene mutation." (PMID 35145081, 2022). "However, epigenetic silencing of MGMT is common in gliomas, and gliomas with low MGMT levels (deficiency and low-expression) are still sufficient to confer TMZ-R, suggesting the existence of an MGMT-independent mechanism of acquired TMZ-R." (PMID 35145081, 2022). "Since it is also capable of passing the blood–tumor barrier in human glioma and its activity is observable in MGMT-methylated and -unmethylated tumors, combination therapy has been explored in several phase I and II trials but failed to improve survival outcome." (PMID 35503461, 2022). "In recent years, with the rapid development of the molecular pathology of glioma, a series of molecular markers, such as IDH mutation, 1p/19q codeletion, and MGMT methylation status, have been considered to be related to the malignancy of glioma and patient prognosis." (PMID 36033495, 2022). "In conclusion, our study demonstrated that APM signature score and APM signature-based risk score could be potential markers in predicting survival outcome, IDH status, 1p19q status, MGMT status, and molecular subtypes of glioma patients." (PMID 35418980, 2022). "The combination of two methods, MSP and qMSP, within the homogenous cohort (IDH1/2wt patients older than 50 years and with surgically resected glioma) gave significant relevance to the prognostic value of the MGMT promoter methylation status in Serbian diffuse glioma patients." (PMID 36361838, 2022). "Further prospective studies are needed on large cohorts of a homogeneous patient population (for example, IDH-wildtype and O6-methylguanine DNA methyltransferase (MGMT) promoter-unmethylated glioma) to independently assess the prognostic impact of TERT promoter mutations." (PMID 35626018, 2022). "Multidirectional changes in the activity of transketolase and hexokinase in the peritumoral zone of glial tumors were revealed in groups with a pronounced IDH1 mutation (significant increase) and with methylation of the MGMT gene promoter (significant decrease)." (PMID 35625744, 2022). "Whether the prognosis of glioma patients with MGMT methylation is related not only to temozolomide sensitivity, but also to the decrease of vascular endothelial permeability needs further study." (PMID 34814870, 2021). "MGMT may lead to drug resistance of tumor cells to alkylating agents by allowing DNA repair to glioma cells." (PMID 34814870, 2021). "MGMT promoter methylation and IDH mutations are strongly associated with TMZ resistance in gliomas." (PMID 33869025, 2021). "NF‐κB or MGMT could serve as potential targets in the treatment of RIP2‐positive TMZ‐resistant glioma." (PMID 33460245, 2021). "Epigenetic modification of MGMT has been well known as a promising prognostic biomarker for glioma." (PMID 34544433, 2021). "We further tested the hypothesis with well-known molecular markers in glioma, including IDH mutation, 1p/19q codeletion, TERT promoter mutations, and MGMT promoter methylation." (PMID 33981597, 2021). "Moreover, we observed that DDX60 was significantly overexpressed in glioma with IDH wild-type, ATRX wild-type, MGMT unmethylated as well as TERT promoter mutated." (PMID 34178649, 2021).
glioma (continued). "A deeper understanding of MGMT transcriptional mechanisms underlying the transcriptional pause and activation, as highlighted here, may provide new avenues to curtail MGMT expression in gliomas." (PMID 34201219, 2021). "MGMT promoter methylation is a prototype example of the terms CpG island methylator phenotype (CIMP) that describes the extensive DNA hypermethylation of promoter-associated CpG islands in human cancers and G-CIMP that denotes the CIMP status in human glioma." (PMID 33801310, 2021). "However, in combination with IDH1 and MGMT mutations, these mutations are good predictors of grade II and grade III gliomas." (PMID 33916593, 2021). "Recent studies have also investigated the potential of radiomics features in predicting other molecular markers for glioma, such as isocitrate dehydrogenase (IDH) mutation, O6-methylguanine-DNA-methyltransferase (MGMT) methylation status, and molecular subgroups." (PMID 34671557, 2021). "Some researchers have demonstrated that the expression levels of MGMT could predict sensitivity to TMZ in patients with glioma." (PMID 34123852, 2021). "Moreover, patients with methylated O6-methylguanine-DNA methyltransferase (MGMT) promoter gliomas benefit much more from temozolomide and radiotherapy." (PMID 34540893, 2021). "MiR-29c regulated SP1 and MGMT expression to enhance glioma cell chemosensitivity to TMZ." (PMID 34316694, 2021). "Since gliomas show distinct molecular hallmarks, we next performed an integrated analysis of PD-L1 TPS and molecular genetic status: IDH mutation, TERT promoter mutation, MGMT promoter methylation and loss of heterozygosity of 1p and 19q (LOH 1p/19q)." (PMID 33963441, 2021). "MGMT methylation was another important prognostic factor in glioma." (PMID 34335936, 2021). "Interference with NF‐κB or MGMT activity could constitute a novel strategy for the treatment of RIP2‐positive TMZ‐resistant glioma." (PMID 33460245, 2021). "Additionally, a recent report shows that TMZ-induced ER stress is dependent on MGMT deficiency which potentiates CD47 blockade and increases glioma cell phagocytosis." (PMID 33391535, 2021). "In grade III glioma, age, histological type, extent of resection, MGMT methylation status, and Ki-67 level were independent prognostic factors that affect OS in patients, and patients with higher preoperative PNI showed a better prognosis only in the univariate analysis (HR = 0.301, p = 0.032)." (PMID 35096561, 2021). "We confirmed that RIP2 can regulate MGMT expression in glioma cells through the NF‐κB pathway." (PMID 33460245, 2021). "One example is the promoter methylation of the gene MGMT (O-6-methylguanine-DNA methyltransferase), coding for a DNA repair enzyme, which was shown to increase sensitivity to drugs such as carmustine and temozolomide in gliomas." (PMID 34805167, 2021). "SD‐36, as well as Stattic, decrease of MGMT protein level in U87 and U251 cells, which indicate that MGMT downregulation may contribute to the synergistic effect of SD‐36 TMZ in glioma cells." (PMID 34291563, 2021). "Additionally, MGMT (O6-methylguanine-DNA methyltransferase) promoter methylation is another example of a glioma signature." (PMID 34336645, 2021). "RIP2 was observed to upregulate MGMT expression in glioma cells." (PMID 33460245, 2021). "We also found that high-risk patients might be more sensitive to TMZ therapy, which may be related to their active IFN pathway down-regulating MGMT level and increasing the sensitivity of glioma cells to TMZ." (PMID 34336837, 2021). "In forty-six glioma patients, the number of IDH mutated patients were 21 (45.7%), IDH wild-type were 25 (54.3%), TERT mutated were 29(63%), TERT wild-type were 17(37%), MGMT promotor methylation were 33(71.7%), MGMT promotor un-methylation were 13(28.3%) respectively." (PMID 34814870, 2021).